LYN (LYN proto-oncogene, Src family tyrosine kinase)
Diseases named in the same sentence as LYN in open-access papers (continued):
Sharing a sentence is not in itself a finding about the gene and the disease.
infectious disease (1 paper, 2022). A disorder directly resulting from the presence and activity of a microbial, viral, or parasitic agent in humans. "And sixteen genes of ‘Antimicrobial Response, Infectious Diseases and Inflammatory Response’ as the top network of RSK2 KO-specific DEGs were shown to have three DEGs highly correlated with RSK2 expression with significant R and p values (ISG15, LYN and STAT5B)." (PMID 36684450, 2022).
LYN also shares sentences with these, for which no sentence is quoted: chronic myelogenous leukemia (4 papers); glomerulonephritis (4); nephritis (4); colon cancer (3); glioblastoma (2); hematologic disorder (2); abortion (1); acute kidney injury (1); airway hyperresponsiveness (1); anaplastic large cell lymphoma (1); Atherosclerotic lesion (1); autoimmune uveitis (1); B-cell lymphoblastic leukemia (1); bacterial infection (1); blood cancers (1); bovine tuberculosis (1); cervical squamous cell carcinoma (1); chronic leukemia (1); diabetic nephropathy (1); endothelial dysfunction (1); eosinophilia (1); erythroleukemia (1); Fever (1); head and neck squamous cell carcinoma (1); Hodgkins lymphoma (1); Hypertension (1); influenza (1); intraepithelial neoplasia (1); kidney disease (1); liver fibrosis (1).
A further 29 diseases each share a sentence with LYN in 1 paper.